CXCR3 (C-X-C motif chemokine receptor 3)
Diseases named in the same sentence as CXCR3 in open-access papers (continued):
Sharing a sentence is not in itself a finding about the gene and the disease.
COVID-19 (continued). "Expression levels of the receptor of MCP-1, C-C motif receptor 2 (CCR2); the receptor for IP-10, chemokine (C-X-C motif) receptor 3 (CXCR3); and the receptor for IL-8, CXCR2 were assessed in the PBMCs from severe or mild COVID-19 patients compared to those from healthy controls." (PMID 33413449, 2021). "Recently, the frequency of CXCR3+CCR6− cTfh1 and CXCR3–CCR6− cTfh 2 cells was found to be higher in COVID-19 convalescent patients than in healthy donors, whereas the levels of CXCR3–CCR6+ cTfh17 cells in COVID-19 convalescent patients were decreased." (PMID 34696395, 2021). "Furthermore, six core gene targets including CAT, NOS2, CXCR3, MAPK1, GPT, and ICAM1 of VA against CHOL/COVID-19 were identified using Cytoscape tool." (PMID 34176789, 2021). "Also, consistently up-regulated is CXCR3, the receptor for CXCL10, one of the soluble mediators most induced in severe COVID-19 blood." (PMID 34433692, 2021). "Therefore, the ligand-receptor pair of PF4_CXCR3 from the interaction between CD14+ monocytes and HLA_DR+ Tregs may contribute to the activation of HLA_DR+ Tregs in COVID-19 patients." (PMID 40114921, 2025). "Serum CXCL9, CXCL10, CXCL11, and CXCR3 levels were significantly higher in patients with severe COVID-19 than in those with non-severe COVID-19; were higher in both patient groups than in the control group; and were higher in patients who died than in those who survived." (PMID 37493737, 2023). "The minimum level of Th17 was observed in patients with severe COVID-19, moreover, within the framework of the general pool of CCR6+ Th17, it was exactly noted in severe patients that there was a decrease in the proportion of CCR4− CXCR3+ Th17.1 cells and an increase in CCR4+ CXCR3—“classical” Th17." (PMID 36674665, 2023). "Other studies have identified CXCR3, CXCR6, and CCR5 as other potential mediators of immune cell trafficking to the lungs during COVID-19 infection, and one of these studies also demonstrated that T and NK cells that expressed these receptors in COVID-19 patients showed greater signs of activation." (PMID 36817450, 2023). "Furthermore, upon bacterial challenge, a similar pattern of cell surface receptor phenotype with reduced expression of CXCR1, CXCR2, CXCR3, CCR1, CCR5 and the maturation marker CD15, with increased expression of CXCR4 and CD66b was found in neutrophils from acute-phase COVID-19 patients." (PMID 35007290, 2022). "Here, we found for the first time that the CXCR3+ population not only increased rapidly in the lung tissue but also in the spleen, PBMCs, and CD8+ cells of old RMs infected with SARS-CoV-2, which appears to be an age-related systemic pathological feature of COVID-19." (PMID 34471088, 2021). "In contrast, CXCR3 levels were still suppressed, in particular in the SC group, raising the possibility that low CXCR3 expression may be a persistent alteration in MAIT cells after COVID-19." (PMID 32989174, 2020). "Consistent with that, the proportion of SARS-CoV-2–specific Tfh1 cells, a subpopulation of Tfh cells characterized with CXCR3+, correlated with the titers of anti-SARS-CoV-2 antibodies, suggesting that Tfh1 cells may positively contribute to the immune response against COVID-19." (PMID 36447270, 2022). "Intracellular IL-21 secretion was significantly increased in TFH cells, CXCR3+ TFH cells, and CXCR3− TFH cells from both COVID-19 convalescents and vaccinees, but not from healthy controls, upon peptide stimulation." (PMID 37802996, 2023). "In the post-COVID-19 dataset (as CD16 was not present in historic flow data used for HCs), total monocyte frequencies also correlated with the CXCR3 chemokine score (r = 0.57, p = 0.016)." (PMID 35151371, 2022). "Similar percentages of CD4+ T cells expressing CCR4, CCR6, CD161, CXCR3, TBET, and GATA3 were found among healthy donors and pregnant women with or without COVID-19." (PMID 34326336, 2021).
rheumatoid arthritis (71 papers, 2004 to 2025). A chronic, systemic autoimmune disorder characterized by inflammation in the synovial membranes and articular surfaces. "CXCL9, acting as a ligand for CXCR3 expressed in synovial mast cells and eosinophils, has been associated with inflammation in synovial tissues and rheumatoid arthritis pathogenesis." (PMID 38650940, 2024). "CXCR3 has been associated with tumor growth in several other diseases such as rheumatoid arthritis, atherosclerosis, and inflammatory skin diseases." (PMID 36479091, 2022). "The majority of CD4+ T helper (Th) cells found in the synovial fluid (SF) of patients with rheumatoid arthritis (RA) express CXCR3, a receptor associated with Th1 cells." (PMID 33066816, 2020). "The chemokine receptor CXCR3 is implicated in a variety of clinically important diseases, notably rheumatoid arthritis and atherosclerosis." (PMID 25425280, 2015). "Conversely, CXCR3 has been found to be upregulated in diseased associated with decerased levels of serum sHLA-G, such as rheumatoid arthritis and lupus." (PMID 20668702, 2010). "Immunostaining of T cells in synovial fluid from individuals with rheumatoid arthritis showed that virtually all of the T cells associated with inflamed joints expressed CXCR3 and CCR5, representing significant enrichment compared to blood T cells from the same participants." (PMID 15526056, 2004). "In rheumatoid arthritis (RA), high CXCR3 expression on mast cells is associated with CXCL9 and CXCL10 expression in synovial fluid from RA patients but not in traumatic arthritis or osteoarthritis patients." (PMID 36275816, 2022). "Initially developed as a CCR5 antagonist to inhibit HIV-1 entry, TAK-779 also antagonizes CCR2 and CXCR3, demonstrating potential for treating a range of Th1 cell-mediated diseases such as rheumatoid arthritis and cancer." (PMID 40786052, 2025). "Its expression drives T cells to atherosclerotic plaques and, in combination with CXCR3, to inflammatory lesions in autoimmune diseases such as rheumatoid arthritis (RA), inflammatory bowel disease (IBD) and multiple sclerosis (MS)." (PMID 36740883, 2023). "In the B‐cell context, studies have demonstrated higher levels of circulating CXCR3 expressing B cells in patients with inflammatory disorders, such as rheumatoid arthritis, giant cell arteritis and polymyalgia rheumatica." (PMID 37927302, 2023). "Similar to rheumatoid arthritis, in arthritis-irAE, SF T cells highly expressed CXCR3 and CXCR6, and their matching ligands, CXCL9/10/11, and CXCL16 were mainly produced by myeloid cells." (PMID 35413951, 2022). "Accumulated B cells in the synovium of patients with rheumatoid arthritis also showed increased CXCR3 expression." (PMID 35794867, 2022). "Previous studies in patients with rheumatoid arthritis and juvenile idiopathic arthritis in an animal model have reported the presence of T cells expressing CXCR3 and CCR6 in synovial tissues." (PMID 35924250, 2022). "On the other hand, it has been reported that TNF-α and IL-6 upregulate the expression of the chemokine receptors CCR5 and CXCR3 on Vδ2 T cells in patients suffering from rheumatoid arthritis." (PMID 34900753, 2021). "CXCR3 and its ligand IP-10 are increased in autoimmune diseases, such as rheumatoid arthritis and multiple sclerosis." (PMID 33224143, 2020). "Both CCR6 and CXCR3 expressing CD4+ T cells have been identified in the synovial fluid of rheumatoid arthritis patients as well as in tissue samples of patients with other autoimmune diseases, such as multiple sclerosis." (PMID 27467144, 2016). "These CXCR3-agonistic cytokines are involved in autoimmune diseases, such as rheumatoid arthritis and systemic lupus erythematosus." (PMID 26506526, 2015). "CXCR3 is a chemokine receptor which has been shown to direct inflammatory cells inside target tissue and drives acute inflammation (synovial tissue in rheumatoid arthritis, liver in autoimmune hepatitis, etc.)." (PMID 26373409, 2015).
rheumatoid arthritis (continued). "CXCR3, a chemokine receptor in the CXC family, has been implicated in the pathogenesis of several chronic diseases including rheumatoid arthritis, multiple sclerosis, dry eye syndrome, and psoriasis." (PMID 24992040, 2014). "Currently, clinical trials using CXCL10 antibody (MDX-1100), are looking promising in patients with ulcerative colitis and rheumatoid arthritis, promoting investigations of the role of CXCR3 in chronic colitis." (PMID 24992040, 2014). "Mast cells preferentially express CXCR3 protein in patients with rheumatoid arthritis and, importantly, this expression is accompanied by elevated level of CXCL9 and CXCL10." (PMID 24278169, 2013). "Most prior efforts aimed at targeting CXCR3 for therapeutic benefit have focused on chronic autoimmune diseases such as multiple sclerosis, inflammatory bowel disease and rheumatoid arthritis." (PMID 22992408, 2012). "CXCR3 inhibitors have been developed and examined in clinical trials for chronic inflammatory diseases such as psoriasis and rheumatoid arthritis." (PMID 19149556, 2009). "Nevertheless, the research on this neutral 8-azaquinazolinone derivative provides important insights for the design of CXCR3 antagonists and may represent a new therapy for rheumatoid arthritis." (PMID 40786052, 2025). "Consequently, CXCRs have been implicated in various diseases; for example, the CXCR3 and CXCR5 receptors have been implicated in autoimmune conditions, such as multiple sclerosis (MS), rheumatoid arthritis (RA), and cutaneous lupus erythematosus (CLE)." (PMID 38256077, 2024). "Moreover, a better understanding of the factors influencing CXCR3 expression would likely also be advantageous for other CXCR3-mediated diseases, such as graft-versus-host disease, rheumatoid arthritis and multiple sclerosis." (PMID 28710387, 2017). "Moreover, CXCL10 and CXCR3 expression is also increased in the synovial membrane of rheumatoid arthritis patients." (PMID 24939012, 2014). "In addition to this compound, there are several other CXCR3 blockers in clinical development for the treatment of rheumatoid arthritis and psoriasis and is extensively reviewed elsewhere." (PMID 25324719, 2014). "Up-regulation of CXCR3 was described on a substantial fraction of peripheral blood B cells from rheumatoid arthritis patients and more importantly, recruitment and accumulation of CXCR3-expressing plasma cells was described in the synovium of patients at early stages of this disease." (PMID 23520491, 2013). "Taken together, the results show that therapy with potent small molecule CXCR3 antagonists may serve as a new strategy for treatment of autoimmune diseases, including rheumatoid arthritis and multiple sclerosis, and to prevent transplant rejection." (PMID 22233170, 2012). "IFN-gamma inducible protein-10 (CXCL10), a member of the CXC chemokine family, and its receptor CXCR3 contribute to the recruitment of T cells from the blood stream into the inflamed joints and have a crucial role in perpetuating inflammation in rheumatoid arthritis (RA) synovial joints." (PMID 21708014, 2011). "Currently, there are several anti-CXCL10 monoclonal antibodies and anti-CXCR3 molecule blockades that are being investigated in clinical trials for autoimmune diseases such as rheumatoid arthritis; however, the therapeutic efficacies of these antagonists in vitiligo patients are currently unknown." (PMID 35096274, 2022). "The CXCL10/CXCR3 and CXCL13/CXCR5 axes are associated with disease activity in several autoimmune diseases including rheumatoid arthritis (RA), systemic lupus erythematosus (SLE) and adult onset Still’s disease." (PMID 29116188, 2017). "Similarly, CXCR3+ cells are involved in rheumatoid arthritis, systemic lupus erythematosus." (PMID 24223818, 2013).
rheumatoid arthritis (continued). "Previous studies have shown that Th1-polarised, CCR5+ and CXCR3+ lymphocytes are enriched in synovial inflammatory infiltrates and in synovial fluid (SF) lymphocytes from patients with adult rheumatoid arthritis (RA) and juvenile idiopathic arthritis (JIA)." (PMID 15743472, 2005). "Both CXCR3 and MCP-1 are known to be increased in chronic inflammatory diseases (e.g., rheumatoid arthritis)." (PMID 39540998, 2024). "Murine and translational studies suggested that CXCR3 and CXCR6 are key elements for effector T cells to migrate into the joints in rheumatoid arthritis, and MDX-1100, anti-CXCL10 monoclonal antibody, showed clinical efficacy in rheumatoid arthritis." (PMID 35413951, 2022). "CD21–/loCD11c+CXCR3+ ABC cells expressing T-bet are increased in SLE, Crohn’s disease, Sjogren’s syndrome, rheumatoid arthritis, common variable immunodeficiency, and multiple sclerosis." (PMID 35531955, 2022). "Another antagonist, TAK-779, which has affinity for CXCR3, CCR5, and CCR2b, has been studied in a mouse model of rheumatoid arthritis." (PMID 36479091, 2022). "The CXCL10/CXCR3 chemokine axis and RANKL/OPG signaling potentially contribute to joint inflammation and bone destruction during rheumatoid arthritis." (PMID 32381074, 2020). "In rheumatoid arthritis, the CD4+CXCR3+CCR6+ subset is known to express high levels of IFNγ with poor secretion of IL-17A,36 though we did not observe any associated cytokine profile in our remission patients." (PMID 31540934, 2019). "In contrast to individuals with rheumatoid arthritis or systemic lupus erythematosus, we found that expression levels of CD24 and CXCR3 on switched CD21+CD24+CD27+CD38intCD95+IgD− memory B cells were reduced in individuals with long-standing diabetes." (PMID 29881878, 2018). "IFN-γ increased the generation of CXCR3+RANKL+ effector B cells, mimicking the synovial B cell phenotype in patients with rheumatoid arthritis." (PMID 26980135, 2016). "Further studies are needed in animal models to explore the therapeutic potential of CXCR3- or CXCL10-antagonists, with the ultimate goal of offering new clues for immune intervention in Th1-mediated diseases such as JIA and rheumatoid arthritis." (PMID 15743470, 2005). "T cell CXCR3 and its ligands CXCL9 and CXCL10 as well as CCR5 and its ligands CCL3 and CCL5 are expressed at higher levels in disorders where Th1 immune responses predominate such as multiple sclerosis and rheumatoid arthritis." (PMID 36670847, 2023). "While rheumatoid arthritis and AD have distinct etiologies, our body of work indicates that CXCL10 or CXCR3 may be promising targets for treating chronic itch." (PMID 31631836, 2019). "We analyzed proportions of Th1 (CXCR3+), Th17 (CCR6+) and TfH (CXCR5+) cells within the CD4+CD45RO+ activated/memory population of a cross sectional group of seropositive Rheumatoid Arthritis patients on stable therapy (Cohort 1), compared to age and gender-matched healthy controls." (PMID 28004828, 2016). "In addition to CXCR3 antagonists, a neutralizing CXCL10 antibody, MDX-1100, is also being tested by Medarex for the treatment of rheumatoid arthritis and is currently in clinical phase II studies." (PMID 25324719, 2014). "Taking the results of this study into consideration in parallel with the studies on rheumatoid arthritis, the CXCL10/CXCR3 pathway may be a candidate as a therapeutic target in human IIMs." (PMID 24939012, 2014). "Serum samples from 49 patients diagnosed with pSS, 33 patients with rheumatoid arthritis (RA), and 30 healthy controls (HCs) were collected for measurements of CXCL9, CXCL10, CXCL11, and CXCR3." (PMID 38900301, 2024). "Based on previous studies, CXCR3 is absent in normal naïve B cells but is upregulated on malignant B cells while CD80 plays an important role for the activation of autoreactive T cells during rheumatoid arthritis." (PMID 30150281, 2018).
rheumatoid arthritis (continued). "Another possibility is that in the pathogenesis of rheumatoid arthritis, CXCL10 acts on CXCR3 rather than TLR4 on macrophages or T lymphocytes to activate ERK, thereby increasing the ability of macrophages or T lymphocytes to migrate." (PMID 37048082, 2023). "Moreover, studies in patients with rheumatoid arthritis (RA) showed that fibroblast-like synoviocytes (FLS) constitutively express CCR2, CCR5, CXCR3,and CXCR4; in addition, stimulation with CCL2, CXCL12, CXCL9, and CXCL10 enhances FLS migration and proliferation." (PMID 28883822, 2017). "Th17/Th22 (CXCR3−CCR4+), Th17.1 (CXCR3+CCR4−), DP (CXCR3+CCR4+), and DN (CXCR3−CCR4−) CCR6+ memTh, cells sorted from PBMC of healthy donors or treatment-naïve early rheumatoid arthritis (RA) patients, were cocultured with SF from RA patients with or without anti-IL17A, anti-IFNγ, or 1,25(OH)2D3." (PMID 34082814, 2021).